CHL1 (cell adhesion molecule L1 like)
Diseases named in the same sentence as CHL1 in open-access papers (continued):
Sharing a sentence is not in itself a finding about the gene and the disease.
renal carcinoma (4 papers, 2011 to 2022). A carcinoma arising from the epithelium of the renal parenchyma or the renal pelvis. "Our data also supported the role of CHL1 as a potentially novel biomarker in the early pathogenesis of two major histological types of renal cancer both CC-RCC and pRCC." (PMID 21408220, 2011). "The estimates of the CHL1 mRNA levels in seven renal cancer cell lines revealed strong down-regulation of this gene: 80-fold (Caki2, KRC/Y), about 1000-fold (TK164) and total silencing (TK10, KH39, HN4, Caki1)." (PMID 21408220, 2011). "The data further supported the role of CHL1 as a potentially novel specific biomarker in the early pathogenesis of two major histological types of renal cancer." (PMID 21408220, 2011). "Our data also supported the role of CHL1 as a potentially novel specific biomarker in the early pathogenesis of two major histological types of renal cancer." (PMID 21408220, 2011). "In addition, CHL1 facilitates the identification of two major histological types of renal cancer as a potentially novel specific biomarker in early pathogenesis." (PMID 29089868, 2017). "The frequency (FD) and the level (LDav) of the CHL1 mRNA decrease in renal cancer (CC-RCC)." (PMID 21408220, 2011). "Therefore we could conclude that the frequency and the average level of the CHL1 expression decrease were similar for two major histological types of renal cancer, CC-RCC and pRCC." (PMID 21408220, 2011). "Since no publications have explored the role of CHL1 in renal cancer in vitro, we conducted experiments in vitro to investigate the role of CHL1 in tumor growth of 786O cells and Caki-1 cells." (PMID 35433461, 2022).
Alzheimer disease (3 papers, 2019 to 2023). A progressive, neurodegenerative disease characterized by loss of function and death of nerve cells in several areas of the brain leading to loss of cognitive function such as memory and language. "Moreover, CHL1 is a neural cell adhesion molecule and a close homolog of BACE1, the rate-limiting enzyme for the production of β-amyloid peptide linked to Alzheimer's disease (AD)." (PMID 36797805, 2023).
breast tumours (3 papers, 2017 to 2024). "Accordingly, an association between low CHL1 mRNA levels and unfavourable histological grade was previously reported in a small series of breast tumours." (PMID 28178655, 2017). "We found higher CHL1 methylation levels in breast tumours than in non-neoplastic tissues, either from mammoplasties or adjacent-to-tumour, which correlated with lower levels of protein expression in tumours measured by immunohistochemistry." (PMID 28178655, 2017).
colon carcinoma (3 papers, 2011 to 2023). "Thus, our results along with the findings that CHL1 was a mutated candidate cancer-associated gene in colon cancer suggested that this type of recognition receptors may indeed have dual roles in carcinogenesis." (PMID 21408220, 2011). "Whether CHL1 plays a potential role in colon cancer development through its regulation of the inflammatory processes of the intestine remains to be elucidated." (PMID 33240104, 2020).
diabetes (3 papers, 2024 to 2025). "CHL1 may be involved in compensatory hyperplasia of pancreatic beta-cells in pre-diabetes and metabolic syndrome." (PMID 38500750, 2024).
endometriosis (3 papers, 2013 to 2023). The growth of functional endometrial tissue in anatomic sites outside the uterine body. "CHL1 participates in the formation of endometriosis through interactions with CHL1-AS1 and CHL1-AS2." (PMID 37455911, 2023). "Conversely, adhesion molecules highly expressed by EEC16 (NCAM and CHL1) but showing only minimal expression in OSEC11 may perhaps be involved in the implantation of endometriosis epithelial cells onto the peritoneum and ovary." (PMID 24502583, 2014).
Fanconi anemia (3 papers, 2013 to 2017). Fanconi anemia (FA) is a hereditary DNA repair disorder characterized by progressive pancytopenia with bone marrow failure, variable congenital malformations and predisposition to develop hematological or solid tumors. "Due to involvement of FANCM, FANCJ and FANCP homologues (Mph1, Chl1 and Slx4), this pathway has been described as a Fanconi anemia-like pathway." (PMID 27636878, 2016).
inflammatory bowel disease (3 papers, 2020 to 2023). A spectrum of small and large bowel inflammatory diseases of unknown etiology. "CHL1-deficiency reduces the recruitment of macrophages and impairs the balance of Th17/Treg cells in mice with inflammatory bowel disease." (PMID 38041124, 2023). "Based on previous reports mentioning an altered inflammation of CHL1−/− mice in mouse models of inflammatory bowel disease, we became interested in immune system-related functions after SCI." (PMID 36411762, 2022). "Our results revealed deficiency of CHL1 exacerbated DSS-induced colitis, and this pathogenesis was potentially mediated by disruption of intestinal barrier integrity, indicating that CHL1 may be an attractive therapeutic target for inflammatory bowel diseases (IBDs) in mice." (PMID 33240104, 2020).
metastatic tumors (3 papers, 2011 to 2024). "CHL1 was found to be one of the most downregulated genes in UM that metastasized to the liver compared to non- metastatic tumors." (PMID 38339073, 2024). "Hypomethylation of CHL1 was also observed in metastatic oral squamous cell carcinoma (OSCC) compared to non-metastatic tumor." (PMID 28243201, 2017). "The majority of such cases (14 of 22, P<0.01) were found in different histotypes of NSCLC (ADC, BAC, SCC) at the Stage I. Also we observed several cases of CHL1 up-regulation in metastatic tumors (stomach, lung, trachea, ovary and uterus)." (PMID 21408220, 2011).
prostate carcinoma (3 papers, 2011 to 2018). A carcinoma that arises from epithelial cells of the prostate gland. "CHL1 gene is located at 3p26, which is demonstrated to be a candidate for prostate cancer susceptibility in Finnish prostate cancer families." (PMID 29568376, 2018). "CHL1 is located at 3p26, a region that is shown to harbor a candidate for prostate cancer susceptibility in Finnish prostate cancer families, although no mutations were detected in the coding part of the gene." (PMID 21408220, 2011). "Significant examples include, a single 14 Kb deletion at chromosome 2: 74,006,259–74,020,290 resulting in a potential novel prostate cancer fusion DUSP11-C2orf11 and a 4 Kb insertion within the CHL1 gene at chromosome 3: 284,661–305,427." (PMID 28423598, 2017).
scoliosis (3 papers, 2014 to 2024). A congenital or acquired spinal deformity characterized by lateral curvature of the spine. "Several genes encoding commissural axon guidance molecules, including ROBO3, EPHA4, CHL1, and DSCAM, are strongly associated with scoliosis." (PMID 37962965, 2024). "This phenotype suggests a role for Camel in the development of the BVS and supports the idea that CHL1 is one of the candidate genes for scoliosis." (PMID 32902807, 2021). "This study revealed a link between Chl1a/Camel and Reissner fiber formation, and this supports the idea that CHL1 is one of the scoliosis factors." (PMID 32902807, 2021). "Thus, it seems quite plausible that CHL1 could be involved in the etiology of scoliosis through disturbance of the central nervous system." (PMID 24512353, 2014). "CHL1 encodes an axon guidance protein related to Robo3, mutations of which could lead to horizontal gaze palsy with progressive scoliosis (HGPPS), a rare disease marked by severe scoliosis." (PMID 24512353, 2014).
Warsaw breakage syndrome (3 papers, 2013 to 2017). A syndrome mainly characterized by severe growth retardation and microcephaly. "It will be interesting to distinguish whether loss of Chl1 helicase function, or loss of a structural role as cohesin interactor, is the cause of Warsaw breakage syndrome." (PMID 27397686, 2016).
adolescent idiopathic scoliosis (2 papers, 2014 to 2021). A scoliosis with no known cause arising in adolescent. "Chl1 has been suggested as a susceptibility gene of adolescent idiopathic scoliosis, although this idea remains short on supporting evidence." (PMID 32902807, 2021). "A previous genome-wide association study (GWAS) suggested a strong association between the single nucleotide polymorphism (SNP) rs10510181 in the proximity of the gene encoding a cell adhesion molecule with homology to L1CAM (CHL1) and adolescent idiopathic scoliosis (AIS) in Caucasians." (PMID 24512353, 2014).
Anosmia (2 papers, 2014 to 2021). An inability to perceive odors. "Finally, a rare single variant in CHL1 (cell adhesion molecule L1-like, chr 3p26.3), acting as co-receptor for NRP1-SEMA3A signal transduction, was recently described in one pedigree presenting CHH and anosmia." (PMID 34502334, 2021).
autism spectrum disorder (2 papers, 2016 to 2023). A spectrum of developmental disorders that includes autism, and Asperger syndrome. "Since CHL1 interacts with D2R and regulates its levels at the cell surface, and since CHL1 is also implicated in autism spectrum disorders, we investigated if treatment of CHL1+/+ and CHL1−/− mice with quinpirole or sulpiride alters their social behavior." (PMID 38025382, 2023).
dementia (2 papers, 2023 to 2025). Loss of intellectual abilities interfering with an individual's social and occupational functions. "Despite most of these being more prominently dysregulated in AD (e.g., SDC4, ITGB2, MIF, and sTREM1), a small subset of proteins showed an opposite effect between these dementias (e.g., CHL1, GPC1, and CNTN5)." (PMID 40866991, 2025). "Among the proteins, APOE, CLU, CHL1, SLC1A3, RAB7A, and CST3 were related to the protein aggregation of misfolded proteins—causative agents and symptomatic of neurodegenerative diseases—such as α-synuclein in PD, and amyloid-β and tau in dementia." (PMID 36797805, 2023).
Down syndrome (2 papers, 2018 to 2019). "In order to further support our finding that increased levels of APP are associated with decreased BACE1-mediated processing of CHL1, we analyzed hippocampal tissue from subjects affected by Down Syndrome (DS) carrying an extra copy of chromosome 21." (PMID 29391027, 2018). "In further support of these findings, we found that elevation of APP was associated with a decreased BACE1-mediated processing of CHL1 in human brains from subjects affected by Down syndrome." (PMID 29391027, 2018). "Moreover, elevation of APP was associated with a decreased BACE1-mediated processing of CHL1 not only in 12 months old 5XFAD mice but also in human brains from subjects affected by Down syndrome, most likely due to substrate competition." (PMID 29391027, 2018). "Furthermore, our findings suggest that BACE1 inhibition could exacerbate mechanism-based side effects in conditions associated with APP elevation (e.g. Down syndrome) owing to impairment of BACE1-mediated processing of CHL1." (PMID 29391027, 2018). "Interestingly, patient no 92 affected by Down syndrome bears also another abnormality on chromosome 3, containing the CHL1 gene known for its major role in establishing synapses in the brain." (PMID 31254375, 2019).
idiopathic scoliosis (2 papers, 2014 to 2021). A scoliosis with no known cause. "Chl1 has been suggested as a susceptibility gene of adolescent idiopathic scoliosis in humans, although other studies failed to support this link." (PMID 32902807, 2021). "And, it provides experimental evidence to support an idea that Chl1 could be a candidate gene for idiopathic scoliosis." (PMID 32902807, 2021). "There was no statistical association between polymorphisms of the CHL1 gene and idiopathic scoliosis in a Chinese population." (PMID 24512353, 2014).
Insulin resistance (2 papers, 2019 to 2021). Increased resistance towards insulin, that is, diminished effectiveness of insulin in reducing blood glucose levels. "In vertebrates, weak expression of L1-CAM is found in adult islets of Langerhans, where the endocrine cells of the pancreas are found, and a single nucleotide polymorphism near the CHL1 locus, another L1 homolog, has been associated with insulin resistance." (PMID 34276554, 2021).
lung adenocarcinoma (2 papers, 2018 to 2021). A carcinoma that arises from the lung and is characterized by the presence of malignant glandular epithelial cells. "In addition, individuals carrying T allele of CHL1 gene had a 1.207-fold risk of lung adenocarcinoma (Additive model: P = 0.030)." (PMID 29568376, 2018). "Moreover, this study manifested that rs425366 in CHL1 gene may increase the risk of lung adenocarcinoma." (PMID 29568376, 2018).
metastatic melanoma (2 papers, 2011 to 2020). A melanoma that has spread from its primary site to another anatomic site. "The Oncomine also showed co-expression of CHL1 with another known cancer metastasis-associated gene, lysyl oxidase (LOX) in metastatic melanoma." (PMID 21408220, 2011). "Given these premises, CHL1 is considered a metastatic melanoma cell line." (PMID 32846966, 2020).
non-small cell lung carcinoma (2 papers, 2021 to 2023). A group of at least three distinct histological types of lung cancer, including non-small cell squamous cell carcinoma, adenocarcinoma, and large cell carcinoma. "Studies have confirmed that in non-small cell lung cancer, exosomal miR-338-3p down-regulates CHL1 expression by inhibiting the activation of the MAPK signalling pathway, thereby inhibiting tumour cell metastasis." (PMID 36447000, 2023). "This study aimed to evaluate the specific regulatory mechanisms of exosomal miR-338-3p/CHL1/MAPK signaling pathway axis in non-small-cell lung cancer." (PMID 34718336, 2021). "Western blotting and qRT-PCR (reverse transcription-polymerase chain reaction) were used to determine the expression levels of CHL1 and exosomal miR-338-3p in NSCLC (non-small-cell lung cancer)." (PMID 34718336, 2021).
pancreatic ductal adenocarcinoma (2 papers, 2023 to 2025). An infiltrating adenocarcinoma that arises from the epithelial cells of the pancreas. "TET1 has been shown to overcome chemotherapy resistance in pancreatic ductal adenocarcinoma by reducing the activity of the cell adhesion molecule L1 like (CHL1)-associated Hedgehog signaling pathway." (PMID 40520993, 2025). "Previous study reported that enhanced RBP TET1 expression could sensitize pancreatic ductal adenocarcinoma cells to 5FU and gemcitabine through inhibiting the CHL1-related Hedgehog signalling pathway." (PMID 36895014, 2023).
pituitary adenoma (2 papers, 2017). "In pituitary adenoma (PA), differential expression of CHL1 may potentially predict a recurrence phenotype." (PMID 29089868, 2017).
skin cancer (2 papers, 2020). "Downregulation of CHL1 was detected in several types of tumors (such as stomach, rectal, colon, small intestinal, pancreatic, kidney, bladder, breast, thyroid, vulvar, and skin cancer), suggesting that CHL1 might act as a putative tumor suppressor." (PMID 33240104, 2020).
squamous cell carcinoma (2 papers, 2021 to 2024). A carcinoma arising from squamous epithelial cells. "The results from THPA (The human protein atlas) further revealed the higher expression of CHL1 protein in adenocarcinoma and squamous cell carcinoma tissues compared to normal tissues." (PMID 34718336, 2021).
uveal melanoma (2 papers, 2014 to 2020). A melanoma derived from melanocytes of the uveal tract. "Several genes, such as HTR2B, CHL1, the ZNF family, YWHAZ and FYN provide potential candidates for distinguishing between uveal melanoma whether contain liver metastases in the future." (PMID 24597767, 2014).
Anxiety (1 paper, 2023). Intense feelings of nervousness, tension, or panic often arise in response to interpersonal stresses. "In the open field, Y-maze and novel object test CHL1−/− male and female mice are delayed in responding to low doses of the D2R agonist quinpirole, whereas anxiety, working memory and novelty-seeking behavior are similar to that of CHL1+/+ males and females." (PMID 38025382, 2023). "We here examined the interplay of D2R and CHL1 in mice and analyzed if their interaction influences novelty-seeking, exploration, anxiety-related behavior, social interaction and locomotor activity." (PMID 38025382, 2023).
autoimmune disease (1 paper, 2023). A disorder resulting from loss of function or tissue destruction of an organ or multiple organs, arising from humoral or cellular immune responses of the individual to their own tissue constituents. "Briefly, some epitopes belonging to MEAF6, CHL1, and ZHX2 were reported to be potentially presented by either class I or class II HLA alleles for which a clear association with autoimmune diseases has been described." (PMID 37512859, 2023).